IL2 (interleukin 2)
Diseases named in the same sentence as IL2 in open-access papers (continued):
Sharing a sentence is not in itself a finding about the gene and the disease.
tumor (continued). "Recently, expression of endogenous IL-2 and IL-2R in the cytoplasm was found to be up-regulated in tumour cells undergoing mitosis." (PMID 10555752, 1999). "Tumour cells treated with IL-2-specific antisense oligonucleotide demonstrated increased apoptosis in comparison to untreated or sense oligonucleotide-treated control cells." (PMID 10555752, 1999). "The treatment was shown to transiently inhibit IL-2 mRNA and IL-2 protein expression as well as proliferation of tumour cells." (PMID 10555752, 1999). "The pretreatment excess of these serum inflammatory markers seems to negatively influence both the host and tumour response to IL-2 administration, by preventing the IL-2-induced lymphocytosis and resulting in tumour progression." (PMID 10408846, 1999). "Twelve of 19 TILs from colorectal hepatic metastases were successfully expanded in vitro in high-dose recombinant interleukin 2 (rlL-2) and their specific anti-tumour cytolytic activity was determined." (PMID 9569042, 1998). "T lymphocytes, activated by interleukin 2 during an anti-tumour response, release soluble interleukin 2 receptors (sIL-2R) into the bloodstream." (PMID 9667652, 1998). "Using reverse transcription polymerase chain reaction (PCR), mRNA for IL-2 was found to be present in tumour cells." (PMID 9083328, 1997). "The findings suggest that the reduced production of IL-2 induced an increase in the production of the PGE2 by progressed tumour lines is involved in the acquisition of resistance." (PMID 8595160, 1996). "Transduction of B16F10 cells (MHC class I and II negative) to express either IL-2 or IL-4 alone delays the formation of tumours, IL-4 being more effective than IL-2." (PMID 8679459, 1996). "The recent use of interleukin 2 (IL-2) and interleukin 4 (IL-4) single cytokine modified tumour cells in rodent models has demonstrated a potential use of these cytokines to produce autologous cancer cell vaccines." (PMID 8679459, 1996). "In comparison, when cells expressing combined IL-2 + IL-4 were injected there were more granulocytes present, and perhaps more importantly, these were mainly localised within the tumour." (PMID 8679459, 1996). "Treatment of established tumours with a single injection of lethally irradiated tumour cells expressing IL-2 + IL-4 was sufficient to either reject tumours, or at least delay further tumour development." (PMID 8679459, 1996). "Preferential cytolytic activity against autologous tumour cells was demonstrated in IL-2-activated MEMNC cultures with excess CD3+ CD8+ cells." (PMID 7917907, 1994). "When tumour-specific CTLs were tested for specific T-cell killing by using only low doses of Interleukin 2 (100 U ml-1), a moderate rate of proliferation frequency of T cells (0.047) and specific cytotoxicity (12%) were observed in lymph node populations." (PMID 7981054, 1994). "This is the first report suggesting that IL-1 beta synergises with IL-2 to induce autologous tumour-specific CD8+ cytotoxic T lymphocytes (CTLs) within the MEMNC population." (PMID 7917907, 1994). "This study was undertaken to investigate the pathways involved in the interleukin 2 (IL-2)-driven growth of tumour-infiltrating lymphocytes (TILs)." (PMID 8198969, 1994). "Tumour objective regression rate was significantly higher in patients treated with IL-2 and MLT than in those receiving IL-2 alone (11/41 vs 1/39, P < 0.001)." (PMID 8286206, 1994). "In vivo administration of a tumour binding SCA-IL-2 should result in a localised high concentration of IL-2 in tumour tissues, maximising the anti-tumour immune response, whilst keeping systemic side effects to a minimum." (PMID 8431359, 1993). "Immunohistochemical analysis of tumour nodules undergoing regression showed stimulation of a largely lymphocytic infiltrate by IL-2 and a macrophage and granulocyte infiltrate, with a small number of lymphocytes by IL-4." (PMID 8347485, 1993).
tumor (continued). "Engineering of a variety of rodent tumour cells to secrete either interleukin 2 (IL-2), or interleukin 4 (IL-4), has been demonstrated to reduce their tumorigenicity." (PMID 8347485, 1993). "The constitutive secretion of IL2 by the tumour cells leads to a reduced or abrogated tumorigenicity in several different tumour models." (PMID 1457368, 1992). "We assessed the correlation between the development of abnormal thyroid function and tumour response in 13 patients receiving IL2 and interferon-2 alpha (IFN2 alpha) for advanced malignancy." (PMID 1931616, 1991). "In a larger group of patients, Tumour Infiltrating Lymphocyte (TIL) growth was established from six of 19 cases using Interleukin-2 (IL-2) and conditioned medium (CM) and resulted in the expansion of TILs up to 100-fold." (PMID 1764393, 1991). "Adoptive immunotherapy with lymphokine activated killer (LAK) cells and recombinant interleukin-2 (IL-2) is successful in a variety of tumour models in both the normal and the immunocompromised mouse." (PMID 2444243, 1987). "LAK cell activity with reduced levels of IL-2 cannot be maintained and anti-tumour effects are lost." (PMID 2444243, 1987). "Allostimulated PBL were cytotoxic for auto-Me in 30/34 cases (85%) whereas IL-2 generated tumour cytotoxic cells in 22/34 cases (64%)." (PMID 3160380, 1985). "The present study was designed to examine the feasibility of in vivo administration of interleukin 2 (IL-2) to induce cytotoxic cell activity against tumours in human subjects." (PMID 6600395, 1983). "Despite promising results from clinical trials, TIL therapy requires complex coordination, including patient selection, tumour procurement, manufacturing logistics, lymphodepletion, and IL-2 administration; all contingent on specialised infrastructure and well-considered integrated care pathways." (PMID 41708938, 2026). "Moreover, PD-1-expressing tumor-infiltrating DCs suppress T cell activity, characterized by a reduction in IL-2 and IFN-γ secretion, as well as T cell proliferation." (PMID 41486149, 2026). "Here, we evaluated whether combining CD39 blockade with other modalities of immunotherapy such as IL-2/anti-IL-2 complexes (IL-2cx) administration could further enhance T cell-mediated antitumor responses and improve tumor control." (PMID 41668741, 2026). "This system allowed for the localized production of IL-2 at the tumor site, where it could enhance T-cell activity and promote anti-tumor immunity." (PMID 41355950, 2026). "Moreover, IL-2 treatment restores the transcription of the E3 ligase FBXO38 in tumor-infiltrating T cells, resulting in reduced PD-1 expression and enhanced T cell function." (PMID 41486149, 2026). "Notably, blocking Siglec-15 would increase the secretion of interferon gamma (IFN-γ) and interleukin-2 (IL-2) both in vitro and in vivo, significantly inhibiting tumor growth." (PMID 41584035, 2026). "Moreover, CAR-T cells cultured with IL-7+15 or IL-2+7+15 maintained sustained cytotoxicity and exhibited increased antitumor cytokine production during repeated tumor challenges." (PMID 41892338, 2026). "Consistently, in vivo neutralization of IL-2 alongside Treg depletion abrogates the induction of IFNγ+ γδ T cell responses, whereas administration of an IL-2Rβγc agonist circumvents Treg-mediated suppression and enhances tumor control." (PMID 42126428, 2026). "We analyzed gene expression patterns and performed repetitive tumor killing assays to assess the ability of CAR-T cells expanded with IL-2 + IL-7 + IL-15 compared with IL-2 alone to maintain proliferation and cytotoxic function across multiple rounds of tumor cell exposure." (PMID 41892338, 2026). "Furthermore, certain antitumor factors, including IL-2, IL-10, and IL-17A, mitigate tumor immune evasion, contributing to improved outcomes." (PMID 40313970, 2025).
tumor (continued). "In addition, some cytokines in the tumor microenvironment such as interleukin-2 (IL-2), interferon-α (interferon-α, IFNα) and interferon-γ (interferon-γ, IFNγ) have also been used in immunotherapy approaches." (PMID 40672947, 2025). "This is an example of how an IL-2 IT can influence the anti-tumor response." (PMID 39852848, 2025). "Unlike interleukin-2 (IL-2), IL-15 avoids stimulating regulatory T cells (Tregs), which can suppress anti-tumor immunity, and is associated with lower toxicity and fewer side effects." (PMID 40520425, 2025). "There is some experimental evidence highlighting the potential of HT to impede tumor progression by modulating the expression levels of IFN-γ, PD-1, IL-17A, and MHC I. Notably, IL-2, IL-10, and IL-17A have been implicated in inhibiting immune escape mechanisms." (PMID 40313970, 2025). "Functional experiments showed that overexpression of the JCHAIN inhibited tumour migration and invasion, which may be closely related to the activation of the IL-2/STAT4 signalling pathway." (PMID 41010015, 2025). "While our in vivo experiments confirmed the potential impact of CXCR4 inhibitor and IL-2 treatments on modulating immune cell dynamics and restricting tumor progression, the precise molecular mechanisms orchestrating these changes require further investigation." (PMID 40698080, 2025). "However, IL-2 alone is insufficient to significantly enhance NK cell anti-tumor activity, potentially due to its role in promoting regulatory T cell (Treg) expansion through IL-2Rα, which is highly expressed in Tregs." (PMID 40063100, 2025). "The increased IL-2 expression in later tumor stages could reflect a compensatory immune mechanism aimed at limiting metastatic progression." (PMID 40869161, 2025). "IL-12, IL-2, and IFN-γ promote Th1 differentiation, which supports antitumor immunity, whereas IL-4, IL-5, and IL-10 drive Th2 differentiation, which is associated with tumor growth and immune suppression." (PMID 40429961, 2025). "The use of feeder cells, such as EBV-LCL which naturally express the ligand for 4-1BB, a stimulatory receptor on NK cells, in combination with the cytokines IL-21 and IL-2, has been shown to be a highly efficient approach for ex vivo expansion of human NK cells with high anti-tumour activity." (PMID 40060948, 2025). "However, IL-2 and IL-15 can be utilized by inhibitory cells including tumor-infiltrating regulatory T cells, which are known to suppress the anti-tumor function of infused CAR T cells." (PMID 40808942, 2025). "In addition, IL-2 is involved in the establishment of anti-tumor immune responses and immune tolerance, plays a crucial role in T-cell development and function, and is central to the progression of a variety of immune-related diseases." (PMID 39958351, 2025). "Some strains, such as Clostridium acetobutylicum DSM792, have been modified to express therapeutic chemicals, such as tumor necrosis factor (TNF-α) and interleukin-2 (IL-2), which further enhance anti-tumor immunity and have direct lethal effects in the tumor microenvironment by inducing T cells." (PMID 40141809, 2025). "A promising radiosensitiser is L-19-IL2, which is an immunocytokine that has been shown in preclinical models to deliver IL-2 to tumour cells via the selective L-19 dependent binding of the extra domain B of fibronectin located on tumour vasculature endothelium." (PMID 41226343, 2025). "On the contrary, we detected a significant increase in several key Th1 cytokines including IFN-γ, IL-2, and IL-15 by the triple treatment, and all of them are crucial for anti-tumor immunity by enhancing the activity of cytotoxic T cells and natural killer cells." (PMID 40104170, 2025). "Mechanistically, compared to IL-2 treatment, Neo-2/15 stimulation significantly reduced the levels of the pro-apoptotic proteins Bax and Bak, and increased the levels of the anti-apoptotic molecules Bcl-2 and Bcl-xl in BBζ co-cultured with tumor cells." (PMID 40025022, 2025).
tumor (continued). "Notably, treatment with Nivolumab induced an inflammatory response primarily in the tumor‐border evidenced by IFNγ, IL‐2, and Perforin secretion alongside increased expression of CD107a on CD8+ T cells, in a donor‐dependent manner." (PMID 40952312, 2025). "Indeed, radiotherapy followed by the intratumoral injection of IL-2 and a tumor-specific monoclonal antibody into the tumor irradiated site (3xTx) can increase the in situ vaccination by recruiting NK cells." (PMID 39852848, 2025). "One of the important mechanisms for this may be that the administration of IL2 leads to an increase in the numbers of certain tumor antigen-specific T lymphocytes." (PMID 41050655, 2025). "Flow cytometry analysis on re-stimulated splenocytes, showed that mice treated with CBL0137 had significantly higher numbers of tumor-specific T cells, as shown by the higher percentages of T cells expressing IL-2, IFNγ or TNFα, particularly in the CD4+ T cell compartment." (PMID 39706891, 2025). "The down-regulation of immune-checkpoint receptors (PD1, CTLA4, TIGIT, etc.), up-regulation of cytokines (IFN-γ, TNF-α, IL2), and activation of granzyme and perforin, etc., remained the primary readouts to characterize the antitumor potential of tumor-infiltrated and activated T-cells." (PMID 40593750, 2025). "IL-2 is crucial in the early stages of an anti-tumor T cell-dominant immune response, though persistently high levels could suppress CD8+ T cell activity by inducing exhaustion or through the maintenance of Tregs." (PMID 40386779, 2025). "Moreover, stimulation of Vδ1 T cells with IL-2 or IL-15 in vitro induces NKp30 and NKp44, augmenting Vδ1 anti-tumor activity against various leukemias." (PMID 40148988, 2025). "Consequently, the NK cells show reduced responsiveness to IL-2 (a molecule that stimulates immune cell activation), diminished cytokine secretion and blunted anti-tumour cytotoxicity—ultimately reinforcing the immunosuppressive state of the TME." (PMID 41429765, 2025). "IL-2-induced reduction of exhaustion markers may therefore be due to its role in preventing tumor-infiltrating CD8+ T cells from commitment to a terminally differentiated fate." (PMID 40502703, 2025). "In conjunction with elevated IL2, which can enhance the cytotoxic activity of NK and T cells, and decreased IL4, which associates with an immunosuppressive TIME, these alterations boost anti-tumor immunity and reverse T cell exhaustion." (PMID 40666944, 2025). "They showed that the optimised strain could modify the tumour microenvironment by doubling intratumoral levels of IL-2 and reducing tumour growth rates." (PMID 40792261, 2025). "Astaxanthin was associated with a higher quantity of tumor‐associated macrophages, infiltration of CD8+ T cells, Tumor Granzyme B, IL‐2, serum TNF‐α and interferon‐γ, genetic transcription of CXCL9, CXCL10, and CXCR3, and mRNA expression of cluster of differentiation." (PMID 40071130, 2025). "In addition, engrafted T cells were functional indicated by the fact that T cells responded to Il-2 ex vivo and rejected implanted tumor cells in vivo." (PMID 41159029, 2025). "CD8+ cytotoxic T lymphocytes eradicate tumor cells through two cooperative mechanisms: the perforin/granzyme pathway induces rapid lysis of target cells, while secretion of cytokines such as IL-2, IFN-γ, and TNF-α establishes a proinflammatory milieu that sustains long-term cytotoxic activity." (PMID 41320679, 2025). "As IL-2 is widely utilized to expand allogeneic NK cells, we hypothesized that combining it with NK-high infusions would enhance the anti-tumor response." (PMID 40063100, 2025). "The enhanced killing phenotype of the NK-92 line is partially explained by the fact the cells are activated with IL-2 and they lack or have lower expression of various NK inhibitory receptors, thus reducing the ability of the target tumour cells to suppress them." (PMID 39791754, 2025).
tumor (continued). "Animal experiments showedthat when transferred to syngeneic recipients, T cells from immunized donorscould mediate tumor regression, and that IL-2 could be used to increase theirnumber." (PMID 40771848, 2025). "This dual mechanism effectively inhibits tumor growth without inducing severe side effects, thereby addressing the systemic toxicity associated with IL-2 therapy comprehensively." (PMID 40009662, 2025). "However, in the early treatment schedule, IL-2/S4B6 significantly prolonged median survival of CT26 tumor-bearing mice (by ∼40%) compared with control treatment and completely cured 1 out of 16 mice." (PMID 40789741, 2025). "Tumor‐derived IL‐2 and TGF‐β convert CD4+CD25− cells into Tregs." (PMID 41143064, 2025). "Especially, the expression profiles of NKG2A and IL-2Rβγ in tumor-infiltrated immune cells of mice were highly similar to those in humans, indicating high reliability and clinical translation of NKG2A-targeted delivery of an IL-2 variant evaluated in mice." (PMID 40170468, 2025). "Notably, the responses observed with IL-2 therapy tend to be durable, with some patients experiencing long-lasting tumor control and improved survival outcomes." (PMID 40046051, 2025). "Additionally, ZEB1 has also been shown to have pro-tumorigenic effects in other components of the TME by mediating interleukin (IL)-2 suppression in tumor-specific T cells." (PMID 41244268, 2025). "Tumor type segregation of correlation analysis showed STS tumor growth correlated significantly with increased serum levels of GM-CSF, IL-2, IL-6, IL-7, IL-18 & MCP-1, whereas increased circulatory CD4+ and CD8+ T cells numbers correlated with STS tumor regression with CPMV treatment." (PMID 40386779, 2025). "Treatment with anti‐CD3/CD28 increased the frequency of CD137+/CD8+ T cells and induced cytokine responses dominated by IFNγ, IL‐2, and Granzyme B. While both non‐tumor and tumor‐border tissue responded to anti‐CD3/CD28, the intensities of immune responses were highly varied." (PMID 40952312, 2025). "Additionally, IL-2 can polarize TAMs to the M2 phenotype, aiding tumor cells in evading immune surveillance and promoting tumor growth and metastasis." (PMID 39958351, 2025). "Innovative IL-2-based immunotherapeutic approaches include immunotoxins, such as antibody–drug conjugates, immunocytokines, and antibody–cytokine fusion proteins that enhance tumor-specific delivery." (PMID 39852848, 2025). "IL-2 exhibited high IHC expression (28.74%) in tumour samples without statistically significant associations were found between IL-2 expression and clinicopathological parameters." (PMID 41465261, 2025). "By promoting both anti-tumor immunity and immune tolerance, IL-2 plays a key role in GC." (PMID 41376630, 2025). "This cellular infiltration is accompanied by robust expression of Th-1-associated cytokines, including IL-2, TNF-α, IFN-γ, and the inducible nitric oxide synthase (iNOS) enzyme, all of which contribute to effective anti-tumor immune responses and tumor clearance." (PMID 40725420, 2025). "Although expansion in the presence of high-dose interleukin-2 (IL-2) results in TIL-ACT products in which tumor-specific clonotypes exhibit attenuated epigenetic or phenotypic features of exhaustion, the transferred TILs can readily reacquire features of exhaustion in vivo post ACT." (PMID 41394272, 2025). "This treatment also induced durable memory responses that protected against tumor re-emergence, illustrating the therapeutic potential of IL-2 agonists that selectively target CD25 on antigen-experienced effector T cells in the context of checkpoint inhibition for cancer immunotherapy." (PMID 40789741, 2025). "One example involved fusing IL-2 to its receptor via a tumor protease-sensitive linker." (PMID 40557148, 2025). "Overexpression of HDAC3 may facilitate tumor cell apoptosis and promote the release of factors such as IL-2 and IFN-γ by activating the CGAS-STING pathway." (PMID 40006729, 2025).